METTL3 (methyltransferase 3, N6-adenosine-methyltransferase complex catalytic subunit)
Diseases named in the same sentence as METTL3 in open-access papers (continued):
Sharing a sentence is not in itself a finding about the gene and the disease.
tumor (continued). "In this study, we show that Mettl3 facilitates BCa progression by mediating tumor angiogenesis in vivo using transgenic mouse model." (PMID 33681207, 2021). "METTL3, the critical component of the N6-methyltransferase complex, has been essential for tumor progression in various cancers." (PMID 33976730, 2021). "In this work, we show that myeloid-specific deletion of METTL3, the catalytic subunit of the methyltransferase complex, enhances tumour growth and metastasis in mouse tumour models and attenuates PD-1 blockade therapy via influencing macrophage reprogramming." (PMID 33654093, 2021). "The elevated levels of METTL3 were shown to promote tumour growth by catalysing m6A methylation of not only mRNAs, but also noncoding RNAs, correlating with tumour stages in primary lung adenocarcinoma samples." (PMID 34638933, 2021). "Here we report decreased expression of the m6A “writer” METTL3 in tumor-infiltrating NK cells, and a positive correlation between protein expression levels of METTL3 and effector molecules in NK cells." (PMID 34535671, 2021). "In a study of liver cancer, the SUMO1 modification of METTL3 promoted tumor progression with high metastatic potential [1041]." (PMID 34573116, 2021). "Consistent with HCC, the tumor-promoting effect of METTL3 has been recently revealed in gallbladder cancer." (PMID 33879256, 2021). "Mechanistically, METTL3 facilitated tumor progression by modulating suppressor of cytokine signaling 2 (SOCS2), RAD52 motif 1 (RDM1) and Snail." (PMID 33879256, 2021). "To further characterize Mettl3 gene expression, we isolated TAMs (CD11b+F4/80+) from tumour tissue and BMDMs from the same host mice and determined that the levels of Mettl3 transcripts in TAMs decreased during tumour progression." (PMID 33654093, 2021). "Here, the authors show that myeloid-specific deletion of Mettl3, the catalytic subunit of the methyltransferase complex, promotes tumor growth and metastasis in preclinical tumor models, influencing macrophage reprogramming and attenuating PD-1 blockade." (PMID 33654093, 2021). "We noted that METTL3 knockdown markedly suppressed xenograft tumor formation and reduced the tumor weight, consistent with the cell cycle assay results demonstrating that METTL3 knockdown exerted inhibitory effects on cell proliferation of PC3 cells in vitro." (PMID 34335955, 2021). "To further confirm the role of METTL3 in NK cell-mediated anti-tumor immunity, we depleted NK cells in WT mice or cKO mice by using anti-asialo-GM1 (ASGM1) or anti-NK1.1, followed by intrasplenic injection of MC38 cells." (PMID 34535671, 2021). "To determine the role of METTL3 in tumour growth in mice, we subcutaneously injected KYSE180 or KYSE450 cells with or without METTL3 depletion or overexpression of WT METTL3 or the METTL3-inactive mutant into athymic nude mice." (PMID 34155197, 2021). "It was demonstrated that METTL3 promoted rapid tumor growth, aggressive invasion, and self-renewal maintenance through different mechanisms." (PMID 33879256, 2021). "As described in a variety of studies, METTL3 is expressed at higher level in tumor tissues compared to normal and we demonstrate here that it is up-regulated also in TETs tissues." (PMID 34530916, 2021). "Further analyses show that METTL3-mediated m6A methylation safeguards signaling pathways downstream of IL-15R, thereby regulating NK cell responsiveness to IL-15 in the tumor microenvironment (TME)." (PMID 34535671, 2021). "It is known that METTL3 participates in all stages of the RNA life cycle and affects tumor formation by regulating m6A modifications of key oncogenes or tumor suppressor genes." (PMID 34497267, 2021). "Studies have shown that the overexpression of methyltransferase 3 (METTL3) exerts a tumor suppressor effect on the proliferation, migration, and invasion of CRC cells through the p38 pathway." (PMID 34127929, 2021).
tumor (continued). "Deletion of Mettl3 in NK cells alters the homeostasis of NK cells and inhibits NK cell infiltration and function in the tumor microenvironment, leading to accelerated tumor development and shortened survival in mice." (PMID 34535671, 2021). "Encouragingly, more rapid tumor growth due to overexpressed METTL3 was inhibited by IGF2BP1 inhibition under cisplatin treatment in vivo." (PMID 34745970, 2021). "METTL3 propelled tumor growth by inducing m6A deposition on the mRNA of oncogenes and rate-limiting enzymes of glucose metabolism." (PMID 33879256, 2021). "Elevation of METTL3 was proved to promote tumor growth, metastasis and therapeutic resistance in an m6A-dependent pattern." (PMID 33879256, 2021). "In an attempt to elucidate the biological function of METTL3 involved in tumorigenesis, we obtained expression landscape of METTL3 across different cancer types with tumor and normal samples from GEPIA database." (PMID 33411363, 2021). "Tumor cells with high METTL3 levels are more likely to respond to DSBs, stabilize their own genome, and maintain their malignant phenotype and drug resistance." (PMID 34485508, 2021). "Compared with xenografts derived from cells expressing the empty vector, the YTHDF2- and METTL3-overexpressing xenografts showed accelerated tumor progression." (PMID 34246306, 2021). "To validate the effect of METTL3 on tumor growth in vivo, we conducted a xenograft tumor assay by subcutaneously injecting nude mice with HCC827 Ctrl, shMETTL3, OE-FBXW7, and shMETTL3/OE-FBXW7 cells." (PMID 33676554, 2021). "Altogether, our study reports the importance of METTL3-mediated m6A methylation in regulating homeostasis and anti-tumor immunity of NK cells through retention of intact IL-15-dependent signaling pathways." (PMID 34535671, 2021). "Compared with the sh-METTL3 + oe-NC group, tumor volume and weight in the sh-METTL3 + oe-HMGA2 group were significantly increased." (PMID 34419065, 2021). "As such, we generated cKO mice with specific deletion of Mettl3 mRNA in NKp46+ cells to investigate the effects of METTL3-mediated m6A methylation on NK cell homeostasis and anti-tumor activity." (PMID 34535671, 2021). "They found METTL3 affected the tumor formation by the regulation the m[superscript 6]A modification in non-coding RNAs." (PMID 34521394, 2021). "We infer that METTL3 can improve the responsiveness of patients to anti-tumor treatments including chemotherapy, anti-vascular therapy and immunotherapy through a variety of signaling pathways." (PMID 34814861, 2021). "METTL3 is the key component of the m6A methyltransferase complex and has recently been reported to be responsible for lncRNA stability in tumor progression." (PMID 34274028, 2021). "Compared to the limited effect elicited by expression of the METTL3-inactive mutant, WT METTL3 overexpression greatly promoted tumour growth." (PMID 34155197, 2021). "Specific depletion of Mettl3 in tumor-associated macrophages(TAM) resulted in CD8+ T cells dysfunction and tumor growth." (PMID 35069586, 2021). "METTL14 performed tumor suppressor functions similar to that of METTL3 in the development of GSCs by targeting mRNA levels of ADAM19, EPHA3 and KLF4." (PMID 34521394, 2021). "METTL3 can interact with the transcription factor eIF3h to promote the translation of oncogenes and ultimately to catalyze and accelerate tumor growth and metastasis." (PMID 33643384, 2021). "As shown, METTL3 knockout cells decreased tumor volumes when compared with tumors in the matched control group." (PMID 35096816, 2021). "More importantly, we distinguished two tumor subtypes based on METTL3 expression and constructed a prognostic model." (PMID 34814861, 2021). "METTL3 regulates specific expression of tumour cells and even induces drug resistance through m6A modification." (PMID 34794452, 2021). "Effects of METTL3 inhibition on anti-tumor immunity should be taken into consideration when evaluating METTL3 as a therapeutic target for cancer therapy." (PMID 34535671, 2021).
tumor (continued). "The tumor growth was significant in mice overexpressing the METTL3 gene compared with the control group." (PMID 34394353, 2021). "Based on the tumor-promoting effect of METTL3, targeting METTL3 is expected to be an effective strategy for anti-tumor therapy." (PMID 33879256, 2021). "The KO mice exhibited significantly faster tumour growth than the WT mice, and the survival of these conditional Mettl3 knockout mice was shortened." (PMID 33654093, 2021). "When METTL3 knockdown SK-Cha-1 cells were implanted, tumor growth was inhibited, and the xenograft tumor weight was reduced, compared to controls." (PMID 34347395, 2021). "In summary, our findings reveal a non-cell-intrinsic, tumour-suppressing function for METTL3, as ablation of METTL3 in macrophages leads to tumour expansion and metastasis." (PMID 33654093, 2021). "Comparing tumor bulk in Upk3aCreER wild-type and KI mice, the mice bearing BCa with overexpressed Mettl3 in Upk3a-derived cells developed tumors more aggressively." (PMID 33681207, 2021). "Consistent with the observations of tumor-infiltrating NK cells, downregulation of METTL3 protein level in NK92 cells induced decreased expression of activation receptors, such as CD69, NKp30, and NKG2D, the transcription factor T-bet, and IFN-γ." (PMID 34535671, 2021). "METTL3 can function as a regulator for chief oncogenes to facilitate tumorigenesis and tumor progression." (PMID 34666602, 2021). "METTL3 is also known to affect tumor formation/progression by the regulation of the m6A at critical oncogene or tumor suppressor transcript sites, and it is considered as a novel pharmacological target for the treatment of several cancers." (PMID 33509238, 2021). "Given the tumor-promoting effects of METTL3, targeting METTL3 brings a bright future for tumor targeted therapy." (PMID 33879256, 2021). "It is worth noting that METTL3 not only was involved in tumor progression but also plays an important role in tumor resistance, especially solid tumors." (PMID 34745970, 2021). "Targeting 1C metabolism has the potential to inhibit malignant tumor behaviors, as shown by the effects of drugs targeting Mthfd2, Shmt2, and Mettl3." (PMID 34298902, 2021). "Specifically, YTHDF1, IGF2BP2, KIAA1429, RBM15, IGF2BP1, ZC3H13, and METTL3 were significantly up-regulated in tumor tissues by unpaired T-tests (P < 0.05), while ALKBH5, YTHDC2, and METTL14 were significantly down-regulated (P < 0.01)." (PMID 34149792, 2021). "Our results showed that METTL3 downregulation had radically suppressed tumor growth and the positive expression of Ki67 with decreased N-cadherin and number of metastatic nodules, and an increased E-cadherin expression." (PMID 34666602, 2021). "In NSCLC, METTL3 has been found to induce drug resistance and the metastasis of tumor cells by promoting YAP translocation." (PMID 34416901, 2021). "The results of open data set and immunohistochemistry showed that the expression of METTL3 in tumor tissues was up-regulated compared with normal tissues adjacent to cancer, and the higher the expression level of METTL3 was, the worse the survival time was." (PMID 34376206, 2021). "METTL3, a major catalytic enzyme in the m6A methyltransferase system, is dysregulated and plays a dual role (oncogene or tumor suppressor) in different human cancers." (PMID 34094960, 2021). "Higher METTL3 is parallel with poor prognosis of patients with BC, suggesting the prognostic value and tumor promoting effect of METTL3 in BC." (PMID 33879256, 2021). "The global transcriptome sequencing with KEGG analysis reveals that Mettl3 is closely related to tumor angiogenesis." (PMID 33681207, 2021). "Compared with the sh-METTL3 + oe-NC group, the number of tumor nodules in sh-METTL3 + oe-HMGA2 group was significantly increased." (PMID 34419065, 2021).
tumor (continued). "In conclusion, our study demonstrates the functional importance and regulatory mechanism of METTL3 in suppressing the tumor growth of TNBC." (PMID 35004298, 2021). "Growing evidence has demonstrated that m6A modification is closely associated with tumorigenesis, tumor differentiation, tumor proliferation, tumor invasion and worse survival in BC patients, including METTL3, METTL14, WTAP, ALKBH5, IGF2BP2, IGF2BP3, and FTO." (PMID 33926554, 2021). "In contrast, METTL3 can serve as a tumour suppressor to inhibit the growth and invasion of ovarian and prostate cancer." (PMID 33932138, 2021). "Recent studies have identified pleiotropic roles of methyltransferase-like 3 (METTL3) in tumor progression." (PMID 34094960, 2021). "PPP2CA expression was significantly decreased in GC tissue (32 tumor samples vs. 32 normal samples; P = 3.76e − 02), while METTL3 expression was increased significantly in GC tissue (415 tumor samples vs. 35 normal samples; P = 7.32e − 06)." (PMID 34485508, 2021). "We further assessed the effect of Mettl3 conditional knockout on tumor weight in vivo and found a marked tendency to reduce in tumor weight." (PMID 33681207, 2021). "Our results demonstrated that METTL3 and miR-20a-5p were downregulated while the NFIC transcriptional level was upregulated in the tumors (P < 0.001), and METTL3 inhibition had suppressed tumor growth (P < 0.001)." (PMID 34666602, 2021). "METTL3 was reported to promote tumor growth and metastasis through functional regulation of NPC related genes." (PMID 33879256, 2021). "Consistently, the m6A methylase METTL3 has been revealed to be highly expressed in BC tissues and cells, while knockdown of METTL3 leads to accelerated apoptosis and suppressed proliferation of BC cells along with inhibited tumor growth." (PMID 33420414, 2021). "The use of STM2457 can reduce the growth of acute myeloid leukaemia, revealing the inhibitory effect of METTL3 as a potential therapeutic strategy for tumours." (PMID 34794452, 2021). "As shown, when compared with paired normal tissue, METTL3 was significantly increased in OS tumor samples." (PMID 35096816, 2021). "Apart from the tumor-promoting effect, several studies had demonstrated the tumor suppressor role of METTL3 in cell migration, implying the role as a double-edged sword of METTL3 in CRC." (PMID 33879256, 2021). "METTL3 can regulate RNA expression in a m6A-dependent manner and contribute to the carcinogenesis, tumor progression, and drug resistance of HCC." (PMID 34046411, 2021). "An increasing number of studies have illustrated that METTL3 is involved in various aspects of tumor progression, including stemness maintenance, tumor growth, invasion, migration, and drug resistance." (PMID 33879256, 2021). "In breast cancer (BRC), elevated METTL3 can promote tumor progression by inhibiting the tumor suppressor let-7g." (PMID 33952721, 2021). "For instance, the m6A methyltransferase METTL3 is over-expressed in gastric, colon and liver cancers and promotes cancer cell proliferation via suppressing the tumour suppressor SOCS2 (Refs 109–111)." (PMID 33787478, 2021). "Three important subunits of the m6A methyltransferase complex, methyltransferase-like 3 (METTL3), METTL14, and WT1 associated protein (WTAP), were found different expression in tumor tissues." (PMID 34178650, 2021). "Previous studies indicated that methyltransferase-like 3 (METTL3), the first methyltransferase to be identified, acted as an oncogene or tumor suppressor in multiple human cancers." (PMID 35096816, 2021). "We examined the expression of methyltransferase-like 3 (METTL3) in tumor specimens using RT-qPCR, immunohistochemistry, and Western blot analysis, and tested the methylation of METTL3 by MSP." (PMID 34497267, 2021). "Taken together, our data demonstrate that overexpressed Mettl3 in bladder urothelium cells or K14+ CSCs escalate the tumor aggressiveness in mouse BCa model." (PMID 33681207, 2021).
tumor (continued). "The METTL3/miR-1246/SPRED2 axis plays an important role in tumour metastasis as abnormal m6A modification of in CRC leads to the upregulation of METTL3 expression, and pri-miR-1246 can be further processed." (PMID 34246319, 2021). "To complement the analyses at mRNA level, we analyzed METTL3 protein expression by immunohistochemistry on thymic tumor tissues (N = 22)." (PMID 34530916, 2021). "METTL3 expression was weak or undetectable in most LUAD samples but was moderate or high in most para-tumor controls, suggesting that METTL3 reduces LUAD tumorigenesis." (PMID 33676554, 2021). "Eighty out of 583 candidate METTL3 targets were preferentially methylated in the tumor tissues of ccRCC patients." (PMID 34631715, 2021). "METTL3 is a predominant methyltransferase for m6A modification and plays an oncogenic role in tumor formation and progression." (PMID 33741902, 2021). "Recently, it was reported that the expression of METTL3 in cSCC was significantly upregulated and that it promoted the expression of the ΔNp63 isoform of p63, which enhanced cSCC cell proliferation and tumor growth." (PMID 34298617, 2021). "In vivo, the tumors from METTL3 overexpression cells grew more rapidly and the tumor weights were heavier, compared with the control cells." (PMID 33431790, 2021). "The expression of m6A-related proteins between the normal and tumor tissues varied among the patients, and the variance of METTL3 was the most dramatic." (PMID 34631715, 2021). "In NSCLC, METTL3 inhibition observably arrested tumor growth and enhanced sensitivity to cisplatin in vivo by reducing YAP1 expression." (PMID 34745970, 2021). "To determine the role of METTL3-induced APC expression downregulation in tumour growth in mice, we subcutaneously injected KYSE180 and KYSE450 cells with or without METTL3 depletion, or with or without combined METTL3 and APC depletion into athymic nude mice." (PMID 34155197, 2021). "Various m6A regulators, especially its methylase METTL3, have been highlighted and identified to be function either as oncogenes or tumor suppressors in diverse cancers." (PMID 33411363, 2021). "Several studies have shown that METTL3 acts as an oncogenic regulator by activating tumor-cell-intrinsic pathways in tumors." (PMID 34616742, 2021). "YTHDF1, KIAA1429, HNRNPC, and METTL3 were most significantly upregulated in tumor samples, and METTL16 and METTL14 were markedly downregulated." (PMID 34975871, 2021). "For example, HNRNPC and METTL3 with CNV deletion in GBM tissue have a relatively higher transcriptome expression level than that in tumor tissue." (PMID 33718217, 2021). "As previous study reported, YTHDF2 induced the targeted degradation of the tumor suppressor to accelerate tumor progression, while this regulation was dependent on METTL3‐medicated m6A modification." (PMID 33411363, 2021). "Similar to the results above, a notably reduced tumor weight was observed with the knockout of Mettl3." (PMID 33681207, 2021). "In BLC cells, METTL3 recruited DGCR8 to promote miR-221/222 maturation via decreasing PTEN expression for tumor growth." (PMID 34745970, 2021). "We further demonstrate the prognostic value of the combination of the METTL3 level in tumour-infiltrating immune cells and CD33+ MDSC density in CC patients, especially for those in advanced disease stages." (PMID 33059689, 2020). "Recently, the overexpression of METTL3 result in HCC tumor progression by repressing SOCS2 through the m6A-YTHDF2 axis in HCC." (PMID 32850303, 2020). "Positive METTL3 expression was observed in 93.0% (53/57) of the tumor and 8.7% (5/57) of peritumoral tissues." (PMID 32626532, 2020). "The down-regulation of METTL3 can weaken the glycolysis ability and cooperate with the glycolysis inhibitor 2-deoxyglucose (2-DG) to inhibit tumor growth in vitro." (PMID 33552994, 2020).